EHMT2 (euchromatic histone lysine methyltransferase 2)
Diseases named in the same sentence as EHMT2 in open-access papers (continued):
Sharing a sentence is not in itself a finding about the gene and the disease.
melanoma (25 papers, 2015 to 2026). A malignant, usually aggressive tumor composed of atypical, neoplastic melanocytes. "One study identified previously unreported recurrent activating mutations (e.g., G1069) in EHMT2, as well as EHMT2 copy number gains in ~26% of human melanomas, which is similar to the pattern of EZH2 gain-of-function mutations." (PMID 33024276, 2020). "Similarly, EHMT2 has been reported to be mutated in cutaneous melanoma and shown to drive melanoma oncogenesis by regulating WNT signaling." (PMID 41366520, 2026). "Similar to EZH2, the histone methyltransferase EHMT2 drives melanoma growth and promotes an immunosuppressive microenvironment by activating the WNT signaling pathway." (PMID 33024276, 2020). "A recent example of histone writer deregulation in melanoma is the histone methyltransferase EHMT2 (also known as G9a)." (PMID 33024276, 2020). "EHMT2 gains/amplifications (≥3 copies) are found in 25.8% of melanomas and 21.1% of colorectal patients (TCGA PanCancer Atlas Colorectal Adenocarcinoma)." (PMID 32512705, 2020). "EHMT2 is overexpressed in breast, prostate, colon, bladder, ovarian, melanoma, lung, and liver cancers." (PMID 25685062, 2015). "KDM6B, BRD2, and BRD3 were moderately to weakly expressed in melanoma samples, whereas weak staining intensity was observed for BRPF1 and EHMT2 in melanoma samples as compared with normal skin tissue indicating that they are significantly expressed at low levels in melanoma samples." (PMID 34771678, 2021). "Similarly, the euchromatic histone-lysine methyltransferase 2 (EHMT2) can drive melanoma growth and promote an immunosuppressive microenvironment by activating the WNT signaling pathway." (PMID 34440824, 2021). "Melanoma cells with high levels of H3K9me2, a histone modification associated with EHMT2 enzymatic activity, were sensitive to the EHMT2 inhibitor UNC0642, indicating a dependency of EHMT2/G9a-amplified melanoma on EHMT2/G9a." (PMID 33024276, 2020). "Furthermore, EHMT2 inhibition in melanoma resulted in increased immune cell-based tumor clearance, indicating a heightened immune response." (PMID 33024276, 2020). "To date, over-expression of EHMT2 may be a prognostic marker for patients with melanoma and esophageal cancer." (PMID 25685062, 2015). "For instance, in primary melanoma, higher expression of EHMT2 also was found when compared to normal skin samples, and knocking down its expression via small interfering RNA significantly reduces cell viability, migration, and invasion in human M14 and A375 melanoma cell lines in vitro." (PMID 34344448, 2021). "Our analysis of publicly available Talantov melanoma datasets revealed that only EZH2, BRD7/9, BRD2/3/4, BRPF1, EHMT2, and KDM6B were significantly overexpressed at the mRNA level in patient melanoma tissue samples as compared to the normal skin samples." (PMID 34771678, 2021). "Interestingly, in several cancer types (not including melanoma), inhibition of EHMT2 resulted in the arrest of cancer cell proliferation and a decrease in cell survival." (PMID 30466474, 2018).
ovarian carcinoma (25 papers, 2014 to 2025). A malignant neoplasm originating from the surface ovarian epithelium. "EHMT2 overexpression has been reported in various types of cancer, including ovarian cancer and neuroblastoma, in relation to cell proliferation and metastasis." (PMID 32028644, 2020). "In the context of ovarian cancer, EHMT2 is frequently amplified and overexpressed and high expression correlates with aggressive peritoneal metastasis and poorer overall survival." (PMID 31775874, 2019). "EHMT2 has been reported to contribute to tumor progression and metastasis in ovarian cancer." (PMID 33050946, 2020). "Moreover, EHMT2 suppression induces autophagy and represses cell proliferation in neuroblastoma or peritoneal metastasis in ovarian cancer." (PMID 27174920, 2016). "We investigated whether a novel dual inhibitor of Ehmt2/Ezh2 methyltransferases (HKMT) was able to derepress expression of critical chemokines and augment immune responses in a murine ovarian cancer model." (PMID 31591445, 2019).
leukemia (23 papers, 2015 to 2025). A malignant (clonal) hematologic disorder, involving hematopoietic stem cells and characterized by the presence of primitive or atypical myeloid or lymphoid cells in the bone marrow and the blood. "EHMT2 exerts methyltransferase activity in AML cells and promotes the transcription of leukemia related genes." (PMID 34409024, 2021).
colorectal cancer (21 papers, 2010 to 2026). A primary or metastatic malignant neoplasm that affects the colon or rectum. "EHMT2 was found mutated in 1.7% of queried colorectal cancer patients." (PMID 32512705, 2020). "Furthermore, inhibition of EHMT2 in microsatellite-stable colorectal cancer can enhance T cell-mediated immune responses via upregulation of galectin-7." (PMID 41366520, 2026). "The depletion of EHMT2 or MBLAC2 sensitized colorectal cancer cells to ribosomal stress." (PMID 41851073, 2026). "Furthermore, the role of EHMT2 in neuroendocrine transformation in non-small cell lung cancer and its role in controlling pluripotent-like identity and tumor-initiating function in human colorectal cancer has also been documented." (PMID 41366520, 2026).
glioblastoma (21 papers, 2015 to 2025). The most malignant astrocytic tumor (WHO grade IV). "In glioblastoma cells, PARP3 has been identified as a novel interactor and regulator of the histone methyltransferase G9a (also known as EHMT2)." (PMID 40741921, 2025). "In the other 6 cancer types (group 2: head and neck, prostate, glioma, cervical, glioblastoma and kidney chromophobe) CDH10 expression was lost or reduced, but this was not correlated with increased EHMT2 expression." (PMID 32292512, 2020).
pancreatic cancer (19 papers, 2014 to 2026). "To more fully establish the role of NK cells in Ehmt2-loss-mediated tumor suppression, we used a Panc02-based pancreatic cancer model propagated in C57BL/6 mice." (PMID 41366520, 2026). "Consistent with this, NK cell depletion reversed the Ehmt2 loss induced tumor suppression in both breast and pancreatic cancer syngeneic tumors in mice." (PMID 41366520, 2026). "Thus, this new knowledge extends the mechanisms underlying the role of the Ehmt2-mediated pathway in suppressing pancreatic cancer initiation and modulating inflammatory pancreatic diseases." (PMID 38948355, 2024). "Human pancreatic cancer cell lines were treated with EHMT2 inhibitors, and NK cell-mediated eradication was analyzed." (PMID 41366520, 2026). "We found that, in the case of pancreatic cancer also, treatment with EHMT2 inhibitors (A366 and UNC0642) resulted in increased NK cell-mediated cytotoxicity, AZGP1 upregulation, and TGF-β1 downregulation." (PMID 41366520, 2026). "We then tested the impact of Ehmt2 knockdown using the pancreatic cancer cell line Panc02-based syngeneic mouse model." (PMID 41366520, 2026). "In a syngeneic pancreatic cancer model, EHMT2 inhibition suppressed tumors in an NK cell-dependent manner, as NK cell depletion restored tumor growth." (PMID 41366520, 2026). "Recently, we have shown that Ehmt2 inactivation in the mouse pancreas alters growth and immune gene expression networks, antagonizing Kras-mediated pancreatic cancer initiation and promotion." (PMID 38948355, 2024). "Recently, we have shown that Ehmt2 inactivation antagonizes oncogenic Kras-mediated pancreatic cancer initiation and promotion by altering growth and immune gene expression networks." (PMID 38948355, 2024). "Inhibition of EHMT2 resensitizes pancreatic cancer cells to GEM in vitro, and the combination of EHMT2 inhibitor and GEM can overcome drug resistance in animal models." (PMID 30577570, 2018). "Therefore, we used the TNBC and pancreatic cancer-based syngeneic models; two cancer types in which, similar to UM, we found that EHMT2 inhibition resulted in increased NK cell-mediated cytotoxicity." (PMID 41366520, 2026). "Additionally, we tested the impact of EHMT2 inhibition on NK cell-mediated pancreatic cancer eradication, which is another cancer type for which adaptive immune checkpoint blockade therapies have not worked as desired." (PMID 41366520, 2026). "Inhibiting EHMT2 in cancer cells, using either pharmacological inhibitors or genetic approaches, enhanced NK cell-mediated killing in several cancer types, including uveal melanoma, triple-negative breast cancer, and pancreatic cancer." (PMID 41366520, 2026). "In addition, we have shown that pharmacological inactivation of both EHMT1 and EHMT2 alters pancreatic cancer cell growth." (PMID 37782747, 2023). "By regulating H3K9me2 levels, EHMT2 plays a role in human pancreatic cancer." (PMID 34249932, 2021). "EHMT2 expression correlates with a poor prognosis also in pancreatic cancer." (PMID 32183227, 2020). "In particular, previous study showed that suppression of PI3K/mTOR inhibited the expression of EHMT2, which is a H3K9 methyltransferase, therefore enhancing the therapeutic response in pancreatic cancer." (PMID 32660632, 2020). "EHMT2 has been demonstrated to regulate also the expression of the CDK inhibitor p27KIP1 via the H3K9 mark, leading to an enhanced response to PI3K/mTOR inhibitors in pancreatic cancer cells resistant to gemcitabine." (PMID 32183227, 2020). "In addition to EHMT2, we found that two other members of the PRMT family, PRMT3 and PRMT6, are highly upregulated in GEM-resistant pancreatic cancer cells." (PMID 30577570, 2018). "In addition, we previously demonstrated that euchromatic histone lysine methyltransferase 2 (EHMT2), a H3K9 methyltransferase, induces autocrine IL-8/CXCR1/2 stimulation in pancreatic cancer cells and paracrine activation of pancreatic stellate cells (PSCs) to increase GEM resistance." (PMID 30577570, 2018).
colon carcinoma (18 papers, 2014 to 2025). "To validate the propionate effect and synergistic effect of cotreatment with SP and an EHMT2 inhibitor (BIX01294) in colon cancer, we used a 3D spheroid model system using a ULA plate." (PMID 34972816, 2022). "Using the RNA-seq results of colon cancer and normal tissues derived from the TCGA portal, we determined the prognostic value of EHMT2 in CRC." (PMID 34972816, 2022). "In summary, propionate in colon cancer decreased the protein stability of EHMT2 by promoting proteasomal degradation." (PMID 34972816, 2022). "Taken together, we suggest that, for colon cancer treatment, if patients use an EHMT2 inhibitor while ingesting a propionate-generating microbiome, we expect a higher anticancer effect." (PMID 34972816, 2022). "Subsequently, EHMT2 downregulation by propionate-induced tumor necrosis factor α-induced protein 1 (TNFAIP1) expression by reducing H3K9me2 levels to promote colon cancer apoptosis." (PMID 34972816, 2022). "Finally, using 3D spheroid CRC models, we identified EHMT2 as a therapeutic target for colon cancer treatment with propionate." (PMID 34972816, 2022). "Thus, the induction of HECTD2 expression by propionate may promote the proteasomal degradation of EHMT2; accordingly, the growth of colon cancer was suppressed by apoptosis induced by EHMT2 reduction." (PMID 34972816, 2022). "Thus, we suggest the anticancer effects of propionate and EHMT2 as therapeutic targets for colon cancer treatment and may provide the possibility for the synergistic effects of an EHMT2 inhibitor and microbiome in CRC treatment." (PMID 34972816, 2022). "Consistent with our result, previous reports also showed that EHMT2 inhibition induced autophagic cell death since suppression of autophagy by an inhibitor or siRNA knockdown reduced BIX-mediated cell death in other cell types including breast, pancreatic, and colon cancer cell lines." (PMID 32028644, 2020).
glioma (18 papers, 2015 to 2024). A benign or malignant brain and spinal cord tumor that arises from glial cells (astrocytes, oligodendrocytes, ependymal cells). "BIX01294, selective inhibitor of G9a/EHMT2, could powerfully mediate autophagy and apoptosis through the mTOR/AMPK/ULK1 pathway in various cancer types, such as gastric, breast, oral squamous carcinoma, glioma, and neuroblastoma." (PMID 33980998, 2022).
neuroblastoma (18 papers, 2014 to 2025). Neuroblastoma (NB) is the most common solid, extracranial childhood tumor. "In a transgenic α‐syn Drosophila model and inducible SH‐SY5Y neuroblastoma cells, α‐syn overexpression increases levels of histone marks associated with heterochromatin, together with levels of EHMT2 (euchromatic histone‐lysine N‐methyltransferase 2, also known as G9a) that acts to modify H3K9." (PMID 31165472, 2019). "Transcriptional analyses indicated that G9a/Ehmt2 gene levels were higher in tumors belonging to the St4 International Neuroblastoma Staging System (INSS) stage compared to patients with St3 and St4s tumors, which can exhibit a better prognosis." (PMID 37894922, 2023). "A previous study has reported that EHMT2 promoted proliferation of neuroblastoma by modulating cellular amino acid metabolism, suggesting a role of EHMT2 in cancer metabolism." (PMID 32028644, 2020). "BIX-01294, an euchromatic histone-lysine N-methyltransferase 2 (EHMT2) inhibitor, has been reported to induce apoptosis in human neuroblastoma cells and inhibit the proliferation of bladder cancer cells." (PMID 25685062, 2015). "Our results show that G9a/Ehmt2 and GLP/Ehmt1 expression is higher in tumors with poorer prognosis, including St4 International Neuroblastoma Staging System (INSS) stage, MYCN amplified NB, and metastatic ES." (PMID 37894922, 2023). "One of the first histone lysine methyltransferase inhibitors (HKMTi), specific against G9a (EHMT2), was BIX-01294, which has been shown to inhibit cell proliferation in BC cell lines and induce apoptosis in neuroblastoma cells." (PMID 31850055, 2019).
viral infection (14 papers, 2014 to 2025). "EHMT2 regulates Drosophila responses to viral infections via the Jak-Stat pathway and that EHMT2 deficient mutants had decreased survival after infection." (PMID 40472016, 2025). "In Drosophila, EHMT2 promotes survival when the organism is subjected to oxidative stress or viral infection, positioning EHMT2 as a key epigenetic regulator of stress responses." (PMID 40472016, 2025). "In other work, in viral infection SP1 regulates HIST1H1C which subsequently modulates EHMT1/EHMT2 complex formation and gene expression." (PMID 35139903, 2022). "Overexpression of JAK1, TYK2, MAP2K1, IFNG, TRPM2, and ADCY9 significantly inhibited viral infection, whereas overexpression of SNX27, GATA4, EHMT2, PCBP2, SMARCA4, and SLX4 enhanced viral infection." (PMID 40530850, 2025). "EHMT2-mediated H3K9me2 activity represses proinflammatory gene (IFN and IFN signalling genes) expression and upon viral infection this repression is relieved to resist the viral infection." (PMID 39509467, 2024). "We did not detect localization of EHMT2 or Ezh2, another epigenetic modifier into viral IBs in response to viral infection indicating that this was not a common observation among all the epigenetic modifiers." (PMID 39509467, 2024). "Inhibition of EHMT2 by gene knockout in mice or inhibition of EHMT1 and EHMT2 with a chemical inhibitor, BIX01294, enhances type I interferon response and protect cells from viral infection." (PMID 25079219, 2014).
bladder cancer (13 papers, 2015 to 2026). "For example, in the case of bladder cancer, the EHMT2/DNMT network has been shown to trigger immune-mediated bladder cancer regression." (PMID 41366520, 2026). "Small molecule inhibitors of EZH2 (a H3K27 methyltransferase) have antimyeloma effects, and inhibitors of G9a (a H3K9 dimethyltransferase, also called EHMT2) have anticancer effects against urinary bladder cancer cells." (PMID 35409271, 2022). "In bladder cancer, high EHMT2 expression is associated with poor clinical outcomes, and a novel dual G9a/DNMT inhibitor, CM-272, reportedly induces apoptosis and immunogenic cell death." (PMID 33436557, 2021). "In summary, BIX-01294, as a specific inhibitor of EHMT2, induces caspase-dependent apoptosis in a dose- and time-dependent manner in human bladder cancer cells." (PMID 25685062, 2015). "Several EHMT2 inhibitors have demonstrated good anti-tumor activity by preventing cancer cell proliferation and inducing apoptosis in many types of tumors, such as T lymphoblastic leukemia cells, bladder cancer, glioma tumor, renal cancer, and so on 10, 19-21." (PMID 33442400, 2021).
multiple myeloma (13 papers, 2018 to 2025). "Among the best synthetic lethal interactions, the euchromatic histone-lysine N-methyltransferase 2 (EHMT2) inhibitor UNC0642 displayed a cooperative effect with carfilzomib (CFZ) in numerous multiple myeloma (MM) cell lines, including drug-resistant models." (PMID 37190128, 2023). "We demonstrated that EHMT2 inhibition also increases PI cytotoxicity in PI-resistant multiple myeloma cell lines, and we found that the level of this interaction is cell-line-dependent, ranging from additive to synergistic." (PMID 37190128, 2023). "To investigate the significance of EHMT2 protein in multiple myeloma pathogenesis, we computationally evaluated its mRNA and protein expression." (PMID 37190128, 2023). "The results suggest that EHMT2 inhibition could be a feasible strategy to increase proteasome inhibitor sensitivity and overcome drug resistance in multiple myeloma patients." (PMID 37190128, 2023). "Next, we considered EHMT2 expression in two microarray databases including a cohort of 20 MGUS, 33 smoldering myeloma, 170 MM, 36 plasma cell leukemia (PCL) patients, and 9 healthy donors." (PMID 37190128, 2023).
Alzheimer disease (12 papers, 2018 to 2025). A progressive, neurodegenerative disease characterized by loss of function and death of nerve cells in several areas of the brain leading to loss of cognitive function such as memory and language. "Taking the critical role of microglia polarization in Alzheimer’s disease into consideration, whether Ehmt2/H3K9me2/CXCL14 axis is also involved in the pathology of other neurological disorders should be discussed in the future study." (PMID 36064768, 2022).
liver cancer (12 papers, 2017 to 2025). An epithelial or non-epithelial malignant neoplasm that arises from the liver. "In conclusion, our in silico analysis revealed a high concomitant expression of the epigenetic genes DNMT1, EHMT2, and UHRF1 in liver cancer patients with inferior outcomes." (PMID 38285887, 2024). "Next, we wanted to evaluate the survival probability of liver cancer patients with high-expression and low-expression of DNMT1, EHMT2, and UHRF1 genes." (PMID 38285887, 2024). "TRERNA1 is also upregulated in liver cancer, and reduces the H3K9 methylation of the promoter region of CDH1 genes to regulate the EHMT2/SNAI1 complex, resulting in the increased tumor metastasis." (PMID 35034562, 2022).
breast tumor (10 papers, 2015 to 2025). "To ascertain whether there was a correlation between EHMT2 and Beclin-1 expression in cancer, we examined the expression levels of EHMT2 and Beclin-1 in breast tumor tissue by Western blotting." (PMID 27174920, 2016). "We observed that EHMT2 was highly expressed in breast tumor tissues." (PMID 27174920, 2016). "SiRNA knockdown in the MDA-MB-231 breast tumour cell line was used to examine the effect of combined inhibition of EZH2 and EHMT2 expression on epigenetic regulation at select target genes, compared to knockdown of either gene alone." (PMID 26300989, 2015).